S100A9 (S100 calcium binding protein A9)
Diseases named in the same sentence as S100A9 in open-access papers (continued):
Sharing a sentence is not in itself a finding about the gene and the disease.
heart failure (11 papers, 2016 to 2025). Inability of the heart to pump blood at an adequate rate to meet tissue metabolic requirements. "Therefore, we speculated that in heart failure caused by β1-AR activation, the upregulation of S100a9 causes autophagy inhibition." (PMID 37723445, 2023). "CatB was a predictor factor in the prediction models of heart failure and liver dysfunction, whereas S100-A9 showed a predictive effect when predicting liver and respiratory failure." (PMID 39049003, 2024). "Of interest, studies in heart failure patients have provided evidence for the presence of HLA-DRneg/low cells within myocardial tissue expressing high levels of S100A9." (PMID 34289931, 2021). "Additionally, the S100a8/S100a9 complex is a useful biomarker for elderly patients with severe heart failure." (PMID 35907209, 2022). "The NLRP3 inflammasome activator, S100A9 has been identified as a promising biomarker and therapeutic target for different cancers as well as for MI and myocarditis, accentuating the relevance of evaluating the potential of anti-S100A9 compounds in clinical studies of cancer and heart failure." (PMID 36466820, 2022). "Recent human studies have suggested that S100A8/A9 levels were elevated in type 2 diabetic patients and indeed, the S100A8/S100A9 complex could be an useful biomarker for the prediction of 1-year mortality in elderly patients with severe heart failure." (PMID 27547188, 2016). "Previous studies have emphasized that elevated plasma levels of S100A9 post-PCI correlate with longer hospital stays and a higher incidence of heart failure in AMI patients." (PMID 40069854, 2025). "Reports suggest that exercise can stimulate macrophages in heart failure mice to secrete IL‐10, promote p‐STAT3/S100A9 nuclear translocation, and regulate the differentiation of myeloid‐derived suppressor cells, thus achieving cardioprotection." (PMID 38504474, 2024). "Moreover, high levels of S100A9 in AMI patients during the first 24 hours post-MI appeared to be related in higher risks of major adverse cardiovascular events and heart failure." (PMID 34490057, 2021).
myocardial ischemia (11 papers, 2022 to 2025). A disorder of cardiac function caused by insufficient blood flow to the muscle tissue of the heart. "Cardiomyocytes can also produce a large amount of S100a9 protein during myocardial ischemia, myocardial hypertrophy, or when stimulated by inflammation." (PMID 37723445, 2023). "Importantly, S100A9 was also elevated in the remote myocardium on day 1 (average 0.96% vs 0.33% in sham controls) showing that the myocardial ischemia induces an inflammatory response of lower intensity in the non-ischemic myocardium as well." (PMID 39009944, 2024).
myocarditis (11 papers, 2021 to 2025). Myocarditis is a condition that is characterized by inflammation of the heart muscle (myocardium). "Conversely, a decrease in serum S100A9 levels was associated with reduced cardiac inflammation, suggesting that low S100A9 levels may indicate a favourable prognosis for myocarditis." (PMID 38504474, 2024). "Patients and mice with CVB3-induced myocarditis have significantly increased levels of S100A8/S100A9, which exacerbate oxidative stress and viral replication in myocarditis, further indicating the important role of neutrophils in the antiviral immune response." (PMID 40176832, 2025). "In experimental research, increased expression of S100A9 mRNA and protein levels were likewise found in the heart and spleen of mice with myocarditis compared to control mice." (PMID 38504474, 2024). "S100A8 and S100A9 have been shown to correlate with different cardiovascular diseases including myocardial infarction and myocarditis." (PMID 32440911, 2021). "In CVB3-positive myocarditis patients, the expression of S100A8 and S100A9 in EMB specimens was associated with bad prognosis." (PMID 32440911, 2021). "Multiple studies have reported that serum S100A8/S100A9 levels derived from neutrophils were elevated in myocarditis, I/R injury, atrial fibrillation, or chronic HF, which can be used as a powerful potential biomarker." (PMID 33680285, 2021). "Additionally, proinflammatory molecules released from monocytes and neutrophils (alarmin S100A8 and S100A9) proved to be significant predictors of myocardial damage, and the highest values in myocarditis were observed in the acute phase of the disease." (PMID 37835816, 2023). "Endomyocardial biopsies from patients with CVB3-positive myocarditis expressed a significant increase in S100A8 and S100A9 compared to healthy controls." (PMID 37175422, 2023). "We recently demonstrated that S100A8 and S100A9 play a pivotal role in human and experimental CVB3-induced myocarditis." (PMID 34065891, 2021). "Furthermore, there is evidence that CVB3-induced myocarditis is influenced by MDSC, which are beside neutrophils and monocytes, the main source of the pro-inflammatory alarmins S100A8 and S100A9, which mainly appear as a heterodimer S100A8/9." (PMID 34065891, 2021). "As an inflammation/immunity mediator, high levels of S100A9 have been indicated and aggravated mutiple pathogen infections, including coxsackievirus B3 (CVB3)-induced myocarditis, streptococcus pneumoniae (SP)-related otitis media (OM), and influenza A virus-related pneumonia." (PMID 34093546, 2021).
oral cancer (11 papers, 2011 to 2025). "Together, both intracellular and extracellular S100A9 exerts a tumor-promoting action through the activation of oral cancer cells and their associated stroma in oral carcinogenesis." (PMID 26315114, 2015). "Despite the presence of S100A8 protein in 3 oral cell lines, only the increase of S100A9-positive cells in tumor stroma was significantly associated with poor differentiation and shortened recurrence-free survival of early-stage oral cancer patients." (PMID 26315114, 2015). "The PCR results showed that expression levels of EMT markers and genes related to metastasis such as S100A8 and S100A9 were significantly decreased after knocking down CD36 in oral cancer cells." (PMID 37207149, 2023). "In OPSCC and oral cancer, S100A8/S100A9 is often downregulated, associated with lower tumor grading, upregulation of apoptosis-related genes, decreased EGFR expression, epithelial differentiation and decreased migration and invasion." (PMID 33469045, 2021). "Elevated expression of S100A9 in oral cancer not only increase tumor invasion but also induce macrophage recruitment." (PMID 34045609, 2021). "The expression of S100A9 in one stromal component, monocytes, stimulated the aggressiveness of co-cultured oral cancer cells." (PMID 26315114, 2015). "The expression of S100A9 protein was differentially increased in 6 out of 7 oral cancer lines relative to NOK and dysplastic oral keratinocytes (DOK) (Top)." (PMID 26315114, 2015). "In this report, the expression of S100A9 in cancer and adjacent tissues from 79 early-stage oral cancer patients was detected by immunohistochemical staining." (PMID 26315114, 2015). "The addition of anti-S100A9 antibodies into the CM attenuated the paracrine effect mediated by S100A9 on oral cancer cell behaviors, particularly the cell invasion, angiogenesis and transendothelial monocyte migration." (PMID 26315114, 2015). "This study provides insights into the selection for early-stage oral cancer patients with concomitant high S100A9 with high CD68 in the stroma that most likely benefit from aggressive treatments." (PMID 26315114, 2015). "We have shown the differential abundance of S100A9 expression in both cancer and stroma cells of oral cancer tissues." (PMID 26315114, 2015). "We also detected the elevation of serum S100A9 levels in early-stage oral cancer patients of a separate cohort of 73 oral cancer patients." (PMID 26315114, 2015). "Immunohistochemical (IHC) staining was used to study the relation of S100A9 expression with the clinicopathologic characteristics and clinical outcome of 79 early-stage oral cancer patients." (PMID 26315114, 2015). "Although a number of putative functions have been proposed for S100A9, its biological role, particularly, in oral cancer cells remains elusive." (PMID 26315114, 2015). "Using similar approach, we verified the interaction of hnRNPD with hnRNPK and S100A9 in oral cancer cells." (PMID 26318153, 2015). "The purpose of this study is to investigate the role of S100A9 deregulation in oral cancer cells and their stroma." (PMID 26315114, 2015). "Together, exogenous S100A9 promoted monocyte recruitment and angiogenesis in addition to oral cancer cell migration and invasion." (PMID 26315114, 2015). "We also detected the elevation of S100A9 protein in the CM from S100A9-bearing TW-2.6 cells and an elevated mean serum S100A9 concentration in 73 oral cancer patients relative to controls, with a significant increase in early-stage patients." (PMID 26315114, 2015). "Early-stage oral cancer patients with both high S100A9 and high CD68 had the poorest clinical outcome relative to those with high expression of either protein alone, or those with low expression of both proteins." (PMID 26315114, 2015).
oral cancer (continued). "Consistent with the pro-tumor role of S100A9 expression in oral cancer cells, stromal expression of S100A9 also significantly enhanced oral cancer migration and invasion while differentially regulating oral cancer proliferation in the co-culture experiment." (PMID 26315114, 2015). "Although S100A9 protein was present in both tumor and stromal cells, only the early-stage oral cancer patients with high stromal expression had reduced recurrence-free survival." (PMID 26315114, 2015). "Together, S100A9 increased IL-6 production through the cross-talk of oral cancer cells with monocytes and the activation of NF-κB or STAT-3 participated in the release." (PMID 26315114, 2015). "Together, the expression of S100A9 in monocytes exerts a pro-tumor effect upon co-culturing with oral cancer cells." (PMID 26315114, 2015). "Co-culture of oral cancer cells with monocytic U937 cells confirmed the increased IL-6 production and the presence of S100A9 enhanced the increase." (PMID 26315114, 2015). "Extraellular S100A9 exerted a stimulatory effect on oral cancer cell behaviors, monocyte transendothelial migration and angiogenesis." (PMID 26315114, 2015). "Tumor associated macrophages (TAMs) have been shown to promote tumorigenesis and metastasis, we used IHC staining to analyze the deregulation impact of CD68 together with S100A9 in tumor stroma on the clinical outcomes of 79 early-stage oral cancer patients." (PMID 26315114, 2015). "Since S100A9 was detected in tumor cells, we ectopically expressed S100A9 in two low- S100A9 oral cancer lines, TW-2.6 and highly metastatic HSC-3, with distinct tumorigenic potential in nude mice." (PMID 26315114, 2015). "Early-stage oral cancer patients with high stromal S100A9 tended to have recurrence relative to the low group (p = 0.01), suggesting a role of stromal S100A9 in cancer recurrence." (PMID 26315114, 2015). "Increased S100A9 expression in oral cancer cells promoted in vitro tumor cell migration and invasion, and in vivo xenograft tumorigenesis." (PMID 26315114, 2015). "Since S100A9 could be released into the extracellular milieu, we also detected the elevation of S100A9 in early-stage oral cancer patient sera." (PMID 26315114, 2015). "The pro-tumor effect exerted by S100A9 in oral cancer was in part via the increase of IL-6 expression and tumor infiltration of G-MDSCs although the involvement of other myeloid cell types and additional cytokines could not be ruled out." (PMID 26315114, 2015). "To address if monocytic S100A9 could impact neighboring cancer cell behaviors, we co-cultured mCherry-expressing oral cancer lines with vector- or S100A9-U937 cells for the indicated time followed by the measurement of mCherry-positive oral cancer cell proliferation, migration and invasion." (PMID 26315114, 2015). "The stimulatory effect of released S100A9 protein on supporting tumor cell proliferation, migration, and invasion, and monocyte recruitment was attenuated by the addition of anti-S100A9 antibodies, demonstrating a paracrine effect exerted by S100A9 on oral cancer tissues." (PMID 26315114, 2015). "Besides supporting the possibility of using this compound for treating oral cancer, the neutralization of IL-6 induced by S100A9 may also function as potent anti-neoplastic agents in oral carcinogenesis, in which the stromal S100A9 plays a significant role in regulating tumor growth and metastasis." (PMID 26315114, 2015). "Taken together, the concomitant increase of both S100A9 and CD68 expression in tumor stroma served as poor prognostic markers for early-stage oral cancer patients." (PMID 26315114, 2015). "High expression of both S100A9 and CD68 proteins in tumor stroma was a strong poor prognostic marker for early-stage oral cancer patients." (PMID 26315114, 2015).
oral cancer (continued). "Early-stage oral cancer patients with both high S100A9 expression and high CD68+ immune infiltrates in stroma had shortest recurrence-free survival, suggesting the use of both S100A9 and CD68 as poor prognostic markers for oral cancer." (PMID 26315114, 2015). "Although the expression of IL-6 mRNA was significantly induced in S100A9 xenograft tissues, there was no enhancement of IL-6 expression and downstream mediators in S100A9-expressing oral cancer monoculture." (PMID 26315114, 2015). "Early-stage oral cancer patients with the increased S100A9 staining in stroma but not tumor cells had significantly reduced recurrence-free survival when compared with those with low expression." (PMID 26315114, 2015). "S100A9 is a calcium-binding protein with two EF-hands and frequently deregulated in several cancer types, however, with no clear role in oral cancer." (PMID 26315114, 2015). "Elevated expression of proinflammatory genes like s100a9, IL23a, IL1b, and immune checkpoint gene PDCD1/PD1 was reported during oral cancer development in the 4-NQO–induced cancer group in comparison to normal mice, and similar results have also been found in human oral cancer and other cancers." (PMID 37936711, 2023). "The differential response to S100A9-mediated cell proliferation and primary tumor formation in nude mice may be explained by the intrinsically different tumorigenic and metastatic potential of HSC-3 from TW-2.6 oral cancer cells, suggesting an early role of S100A9 in oral carcinogenesis." (PMID 26315114, 2015).
osteoarthritis (11 papers, 2006 to 2024). A noninflammatory degenerative joint disease occurring chiefly in older persons, characterized by degeneration of the articular cartilage, hypertrophy of bone at the margins and changes in the synovial membrane. "Mice deficient in S100A9 show low mobilization of monocytes into synovium compartment in knees with collagenase-induced osteoarthritis." (PMID 31752076, 2019). "Mice deficient in S100A9 show mild osteoarthritis syndrome upon destabilized medial meniscus-meniscus surgery as compared to wild-type mice." (PMID 31752076, 2019). "Intra-articular injection of S100A8 increased canonical Wnt signaling, whereas canonical Wnt signaling was decreased after the induction of experimental osteoarthritis in S100A9-deficient mice." (PMID 28630526, 2017). "S100A8 and S100A9 are well-known inflammatory plasma proteins involved in the inflammatory disorders, including osteoarthritis." (PMID 38248784, 2024). "S100A9 plays an essential role in the development of experimental osteoarthritis (OA), and S100A9 expression is differentially up‐regulated in chondrocytes, in the early stages of surgical induction in an OA model." (PMID 33734570, 2021). "S100A9 induces a proinflammatory macrophage phenotype in osteoarthritis." (PMID 34890276, 2022). "Moreover, an increase in S100A9 in the synovium was observed in a collagenase‐induced osteoarthritis mouse model." (PMID 33734570, 2021). "Increasing evidence has shown the S100A9 exacerbation of degenerative joint diseases." (PMID 31752076, 2019). "In addition, accumulating evidence has revealed the relevance of S100A9 to arthritic diseases, like osteoarthritis, rheumatoid arthritis, and psoriatic arthritis." (PMID 31752076, 2019). "Moreover, S100A9—an alarmin mainly produced by activated neutrophils—induces the secretion of proinflammatory cytokines and matrix metalloproteinases (MMPs) by synovial MACs in osteoarthritis." (PMID 38334600, 2024). "In RA and osteoarthritis patients, three S100 proteins, including S100A8, S100A9, and S100A12 are the most up-regulated biomarkers." (PMID 35796625, 2022). "However, both S100-A8 and S100-A9 were decreased in the serum of LCPD patients, showing that LCPD has a different pathogenesis to osteoarthritis." (PMID 26438379, 2015).
acute myeloid leukemia (10 papers, 2018 to 2024). Acute myeloid leukemia (AML) is a group of neoplasms arising from precursor cells committed to the myeloid cell-line differentiation. "In acute myeloid leukemia, S100A8 not only inhibits S100A9-induced terminal differentiation of acute myeloid leukemia (AML) cells, but also favors AML growth." (PMID 36906583, 2023). "Modifying the S100A8/S100A9 ratio by blocking S100A8 with antibodies or adding S100A9 induces the differentiation of acute myeloid leukemia cells and their growth arrest in mouse and human models." (PMID 31437241, 2019). "Interestingly, Ltf and Ngp, which are induced upon myeloid differentiation, and S100a9, which induces differentiation of acute myeloid leukemia cells were downregulated in LSCs isolated from the spleen compared to those from BM." (PMID 36163264, 2022). "S100A9 stimulates pro-inflammatory cytokine secretion, neutrophil phagocytosis, degranulation of secretory and specific/gelatinase granules and phagocyte migration and promotes the differentiation of acute myeloid leukemia cells." (PMID 31437241, 2019). "Numerous data from the literature suggest that there is a deregulation of the expression of coding genes for S100A8 and/or S100A9 in acute myeloid leukemia (AML)." (PMID 33801279, 2021). "However, Laouedj M found that S100A9 could induce differentiation and maturation of acute myeloid leukemia cells." (PMID 34045609, 2021). "S100A9 induces acute myeloid leukemia (AML) cell differentiation through TLR4–MAPK/ERK–JNK signaling, whereas S100A8 prevents differentiation induced by S100A9 activity and maintains the AML immature phenotype." (PMID 29942307, 2018). "Studies on hematological malignancies have found that the expression levels of S100A8 and S100A9 were markedly increased in acute myeloid leukemia (AML), and high expression of S100A8 was a poor prognostic factor for AML patients." (PMID 35371990, 2022). "In mice models of acute myeloid leukemia (AML), S100A8 antibodies, but not S100A9 antibodies, induce AML cell differentiation, decrease leukemic burden and increase survival." (PMID 33801279, 2021).